SNORD65C (small nucleolar RNA, C/D box 65C)
Gene: Small nucleolar RNA gene on chromosome 7 (23,396,446 to 23,396,516, forward strand). Ensembl gene ENSG00000212264.
Gene Ontology:
Biological process: RNA processing
Cellular component: nucleolus
Homologues: Orthologues: chimpanzee SNORD65C (99% identical), macaque SNORD65C (99% identical), rat LOC120099030 (82% identical). Paralogues in human: SNORD65 (92% identical), SNORD65B (83% identical).